AR (androgen receptor)
Diseases named in the same sentence as AR in open-access papers (continued):
Sharing a sentence is not in itself a finding about the gene and the disease.
cancer (continued). "In summary, we evaluated both primary cancer patients and Met/CRPC patients for the presence of TMPRSS2/ERG rearrangements, AR gene copy number gain, and PTEN deletion using a three-marker FISH panel." (PMID 24098661, 2013). "Scoring data from Wnt5a, AR, VEGF and Ki-67 immunostained cores from benign and cancer tissues in duplicates mounted in a TMA." (PMID 22039506, 2011). "We will review its structure and function, crosstalk with androgen receptor signaling, and regulation of INPP4B expression, as well as existing data about its role in cancer." (PMID 21487159, 2011). "The difference between AR, Ki-67 and VEGF staining intensities in cancer versus benign cores was statistically significant (p<0.0001) when Wilcoxon rank sum test was performed." (PMID 22039506, 2011). "Patients with AR-V7 mRNA levels in Q4 had significantly shorter cancer-specific survival after metastasis surgery than the other CRPC patients and a similar outcome was seen for patients with detectable levels of the AR-V567es in comparison with the rest." (PMID 21552559, 2011). "Our pan-cancer analysis revealed a strong negative correlation between AR activity and immune infiltration in both bulk RNA-seq and single-cell transcriptomic data." (PMID 41486951, 2026). "Subsequently, we compared AR activity levels between nonresponders and responders in these cancer cohorts." (PMID 41486951, 2026). "The remaining cancer types did not exhibit significant differences in the relationship between AR activity and PFI outcomes of patients with cancer." (PMID 41486951, 2026). "Once again, AR activity showed a negative correlation with immune cell infiltration across cancer lineages." (PMID 41486951, 2026). "As we found that FOXA1 alterations were also modestly frequent in breast, bladder, and salivary cancers, subsets of which also express the AR, it is logical to test our classification scheme in nonprostatic cancers moving forward." (PMID 39745364, 2025). "Furthermore, TBX21 protein levels were evaluated in a panel of prostate cell lines, including normal prostate epithelial RWPE-1, AR-positive (LNCaP, 22RV1), and AR-negative (PC3, DU145) cancer cells." (PMID 41573646, 2025). "Mifepristone is a highly potent steroidal glucocorticoid receptor (GR) and progesterone receptor (PR) antagonist as well as a moderately potent androgen receptor (AR) antagonist that is not currently approved for the treatment of cancer." (PMID 40779028, 2025). "Further, the exploration of valine–niclosamide’s activity against NF-kB, STAT3, KRAS, and other oncogenic pathways that demonstrate rebound activity following AR-KO is necessary in HCC, PCa, and other cancers to demonstrate the maintenance of key types of activity across cancer types." (PMID 40805231, 2025). "When exposed to CM from C1 cultures, PCa cells proliferated at similar rates to control media, regardless of their AR status, indicating that C1 cultures do not significantly influence cancer cell growth." (PMID 41327318, 2025). "There was a strong positive association between AR expression and MTAP expression in all cancers as well as in subsets of ERG negative and ERG positive cancers (p < 0.0001 each)." (PMID 40554389, 2025). "Furthermore, TIGIT potentially inhibits DNA damage (16%), hormone androgen receptor (AR) (16%), and receptor tyrosine kinase (RTK) (12%) pathways in pan-cancer." (PMID 40076932, 2025). "Since ferroptosis is driven by iron-dependent lipid peroxidation, we hypothesized that AR could suppress this process by downregulating LTFe and its downstream target LTF, thereby promoting cancer cell survival." (PMID 40082405, 2025).
cancer (continued). "Beyond direct AR inhibition, novel strategies such as regulated induced proximity targeting chimeras (RIPTACs) exploit AR as a means to selectively induce cancer cell death without directly antagonising receptor activity." (PMID 41374958, 2025). "Early clinical trials targeting the androgen receptor, estrogen receptor, and BTK (Bruton tyrosine kinase) have demonstrated encouraging efficacy and safety profiles, highlighting the potential of protein degraders as a new class of cancer therapeutics." (PMID 40558489, 2025). "Due to the homing effect of the AR peptide, the prepared nanomaterials could effectively accumulate at the site of MCF-7 cancer cells." (PMID 40497249, 2025). "Therefore, this system leverages the enhanced targeting induced by the AR peptide to achieve a combination of chemotherapy, PDT, and PTT for the inhibition of MCF-7 cancer cell growth." (PMID 40497249, 2025). "Neither of the two ER- and AR-positive cancer samples exhibited elevated BCL6 levels in our analysis." (PMID 40729351, 2025). "Necroptosis induction contributes to suppressing therapeutic resistance in cancer stem cells, thus we evaluated whether the identified targets WT1 and FOXA1, which have an impact on stemness by targeting AR, could also play a role in necroptosis activation." (PMID 40399259, 2025). "Simultaneous PP2A activation and importin inhibition reduces nuclear levels of proteins that drive cancer progression and therapeutic resistance such as JUN, YAP, MYC, androgen receptor, hnRNPA1, and NF-κB under conditions where compounds that target PP2A or KPNB1 individually are inactive." (PMID 40588551, 2025). "These constitutively active AR isoforms drive cancer cell proliferation in the absence of circulating androgens or ligand stimulation." (PMID 41235005, 2025). "In the next section of this review, we will outline the known involvement of T and AR in cancers originating from non-reproductive systems and attempt to understand their possible role in sex disparity." (PMID 41228208, 2025). "One of the limitations of our study is the absence of AR-positive and ER-negative cancer samples for comparative expression analysis." (PMID 40729351, 2025). "We also show that activated OPTN has a potential activating effect on the activity of EMT (25%) and Apoptosis (16%) pathways, as well as a potential inhibitory effect on the activity of the Cell cycle (19%), DNA damage (16%) hormone AR (16%) and PI3K/AKT (12%) in pan-cancer." (PMID 39859167, 2025). "Therefore, we are interested in detecting the expression of AR and PSA in PC3 cancer cells by green tea extract." (PMID 40336533, 2025). "A landmark study demonstrating no cancer development in the bladder of AR knockout mice treated with a strong chemical carcinogen N-butyl-N-4-hydroxybutyl nitrosamine (BBN) indicated a critical role of AR in promoting urothelial carcinogenesis." (PMID 40486871, 2025). "Conversely, CM from C3 cultures, which are linked to poor clinical outcomes, significantly increased the proliferation of both AR-positive and AR-negative PCa cell lines suggesting that C3 cultures promote cancer cell growth." (PMID 41327318, 2025). "However, in certain cases, despite androgen deprivation therapy (ADT), cancer could progress to Castration-Resistant Prostate Cancer (CRPC) due to: AR gene amplification, AR mutations and splice variants, intratumoral androgen synthesis or activation of AR by other signaling pathways." (PMID 41228293, 2025).
cancer (continued). "Since androgen levels and perhaps also AR levels differ between males and females, it is of great interest to determine whether androgens, particularly T, and AR are linked to sex-specific differences in the incidence and survival outcomes of cancers arising in non-reproductive tissues." (PMID 41228208, 2025). "Additionally, androgen receptor (AR) and progesterone receptor (PR) positive cases had higher levels of TBL1XR1 expression in the nuclear of cancer cells." (PMID 38347836, 2024). "Interestingly, we observed the overexpression of AR in KGN cells compared to HGrC1 cells, which is characteristic of AGCT tumors and other AR-positive cancers." (PMID 39456756, 2024). "Osteoblasts have been reported to secrete the adrenal androgen precursor dehydroepiandrosterone (DHEA), which does not induce the androgen receptor (AR), but promotes cancer progression and metastasis." (PMID 38464516, 2024). "NRs such as AR, estrogen receptor (ER), farnesoid X receptor (FXR), glucocorticoid receptor (GR), hepatocyte nuclear factor 4 alpha (HNF4α), liver X receptors (LXR), PPARs and pregnane X receptor (PXR) function as regulators of both inflammation and cancer." (PMID 39199690, 2024). "Novel to this study, we identify ANO7 as a potential oncogenic driver in African men, through the formation of gene fusions with the cancer-related genes G3BP1 and PPFIA4, involved in androgen receptor (AR) and mitogen-activated protein kinase (MAPK) signalling, respectively." (PMID 37749167, 2024). "Three out of four cell lines displayed epithelial characteristics, however without expression of prostate (cancer) characteristics, e.g., androgen receptor." (PMID 38704600, 2024). "Across most cancer types, a positive correlation was identified between GSVA scores and EMT and RAS/MAPK pathways, while a negative correlation was identified with cell cycle, DNA damage, and AR pathways." (PMID 38584831, 2024). "Moreover, in cancer cells, HOXB13 promotes increased expression of AR and NKX3-1 through its central role in recruiting SWI/SNF chromatin remodelers to their cognate super-enhancers." (PMID 38201640, 2024). "It is through the optimally coupled use of these two evolutionarily adaptive capacities—centrosome amplification and centrosome clustering—that cancer cells have the highest dividend and the transcription factor FOXM1 offers AR-low TNBC cells this critical capacity." (PMID 39335162, 2024). "Additionally, AR-DHT signaling has been shown to influence cell proliferation, differentiation, and apoptosis, thereby playing a significant role in various cancers, including prostate and gastric cancers." (PMID 39335190, 2024). "Special attention is given to estrogen receptor-positive (ER+) and estrogen receptor-negative (ER−) tumors, androgen receptor signaling, and the dual role of progesterone in both promoting and inhibiting cancer progression." (PMID 38362126, 2024). "Owing to the exceptional response of the patient’s cancer to alectinib, the patient did not receive androgen receptor blockade therapy." (PMID 39659799, 2024). "DHT binds with an AR, leading to the translocation of this DHT‐AR complex into the nucleus and increases the cell cycle genes' transcription rates, resulting in the proliferation of cancer cells." (PMID 39410867, 2024). "Reassuringly, individuals harboring a heterozygous variant in a predominately AR gene, CTC1 or WRAP53, and including DKC1 (females), were not at increased risk of cancer." (PMID 39661387, 2024).
cancer (continued). "This suggests that targeting RCC1 might have potential in combinatory therapy with first-line anti-cancer drugs like EGFR inhibitors, mTOR inhibitors and AR inhibitors, whose effectiveness are often compromised by increased cytoplasmic distribution of Skp2." (PMID 38561375, 2024). "As ~90% of PCs are dependent on AR signaling at diagnosis, ADT initially inhibits cancer cell proliferation by lowering circulating testosterone concentrations, but ~10–20% of cases will progress and develop castration-resistant prostate cancer (CRPC) within 5 years." (PMID 39591176, 2024). "The pathway association network suggested that all disulfidptosis-related genes may play a role in cancer-related pathways, including cell cycle, DNA damage, EMT, AR, and ER pathways." (PMID 38584831, 2024). "Next, we investigated expression of epithelial prostate (cancer) markers KRT, AR and EpCAM." (PMID 38704600, 2024). "A more precise model of clinical PCa requires, at the very least, an AR-positive cancer cell line with weak or no androgen sensitivity." (PMID 39768760, 2024). "Carcinoma of apocrine differentiation is characterized by an AR positive, SOX10 negative, K5 negative or focal immunophenotype." (PMID 37306115, 2024). "Carcinoma of apocrine differentiation consistently demonstrates an AR positive, SOX10 negative, K5 negative or focal immunophenotype." (PMID 37306115, 2024). "Carcinoma of apocrine differentiation demonstrated an AR positive, SOX10 negative, K5 negative/focal immunophenotype." (PMID 37306115, 2024). "As the focal amplification at the AR gene locus is not present in the original cancer in 2012 but shared by all subsequent samples, it must have occurred in the intervening period between 2012 and 2015." (PMID 37628903, 2023). "By dissecting cancer gene expression driven by the truncated TG2 isoform and the canonical one, an unbiased new link between TG2 and MUC1 has been established and regulation of MUC1 via transcriptional repression of AR by TG2 revealed for the first time." (PMID 37160910, 2023). "They likely represent stages of a continuous process where cancer cells lose their specialized characteristics, acquire stem cell-like properties, and eventually become independent of and resistant to AR signaling." (PMID 37446279, 2023). "Together, ATAD2 acts as a transcriptional co-activator of ER and AR, regulating the expression of ER/AR-targeted genes to control cancer cell proliferation and survival 84, even without gonadal hormone stimulation." (PMID 36632213, 2023). "Many models of aggressive cancer are representative of neuroendocrine malignancies and do not express AR." (PMID 37626712, 2023). "Knockdown of JMJD6 reduced cancer cells, AR-V7 levels and U2AF65 recruitment to AR pre-mRNA." (PMID 37228649, 2023). "As a result, the AR remains in the cytosol without nuclear translocation, inhibiting the necessary transcription cascade for promoting cancer cell proliferation and ultimately triggering cellular apoptosis." (PMID 37273124, 2023). "Below, we summarize our comprehensive review of studies on AR-SV expression and function in multiple non-prostatic malignancies, non-cancer pathologies, and normal tissues in humans and non-human species." (PMID 37626712, 2023). "In more detail, the expression of AR was significantly higher in the right-sided non-tumorous tissues obtained from males diagnosed with early-stage cancer compared with their corresponding female specimens (P< 0.01)." (PMID 37206439, 2023). "However, the expression of AR was equal between proximal (358.3; IQR: 256.4 – 388.3) and distal (357.5; IQR: 279.4 – 389.8) cancers." (PMID 37206439, 2023). "The degradation of AR attenuated DHT-induced AR transactivation, suppressed gene expression including AR-V7 specific targets, and resulted in efficient growth inhibition specific to cancer cells." (PMID 36893587, 2023).
cancer (continued). "Condensation fails to promote the degradation of androgen receptor located in the nucleus, leading to activation of cancer progression." (PMID 36875159, 2023). "Although these cancers become refractory to ADT, CaPs retain a functional androgen receptor (AR)." (PMID 36765857, 2023). "For example, studies over the past several decades indicate that treatment-naïve PCa has both AR-expressing (AR+) and AR low-/non-expressing (AR−/lo) cancer cells as reviewed." (PMID 37596619, 2023). "Furthermore, we identified NADBPs that are known (ATIC, AR and IDH2),as well as potential new drug targets in cancer (FH and NT5C2)." (PMID 36880517, 2023). "Several studies on PCa indicate AR phosphorylation regulates both the genomic and non-genomic AR activity to drive cancer cell proliferation, survival, and invasiveness." (PMID 38203649, 2023). "Both TNBC and HER2-positive carcinomas can exhibit apocrine differentiation, which is generally characterized by being estrogen receptor-negative and androgen-receptor (AR)-positive." (PMID 38023167, 2023). "Here we found AR expression in RCC cells decreased in response to hypoxia, which might then lead to increase the cancer stem cells (CSC) phenotype through the lncTCFL5-2-modulated YBX1/SOX2 signals." (PMID 36397101, 2022). "We also discovered that AR represses the IL1β gene by binding an androgen response element half-site located within the promoter, which explains the IL1β expression in AR-negative (ARNEG) cancer cells." (PMID 36561929, 2022). "AR/AR expression in GBM and other cancers has already been the focus of many studies." (PMID 36361793, 2022). "Notably, the approval of two potent AR-pathway inhibitors (ARI), enzalutamide and abiraterone, has led to an increase in patients with mCRPC presenting with contingents of ARNEG cancer cells." (PMID 36561929, 2022). "Androgen receptor (AR) is a known target of Celastrol to induce autophagy in cancers, but its role in PD is not understood." (PMID 35309340, 2022). "AR, MIF, HSP90B1, and MAOA were expressed in more than 50% of cancer cells with high expression levels and may have potential therapeutic targets." (PMID 36452480, 2022). "The released AR siRNA silenced AR expression and effectively blocked the AR pathway, while DTX promoted the assembly of microtubule dimers into microtubules and stabilized the microtubules, thereby inhibiting mitosis and the proliferation of cancer cells." (PMID 35631549, 2022). "Here, AR also regulates TGFB secretion, which may have bearing on how hospitable cancer cells find the bone." (PMID 37435460, 2022). "Some cell markers such as EGFR, PSMA, PSA, AR, CD133 (stem cell marker), and E-cadherin (EMT) have been used without a clear association to predict cancer outcomes." (PMID 35207452, 2022). "Although there was no shared gene among the three groups in the Cancer-related pathways, three genes were shared between the two malignant groups namely AR, HSP90AB1 and GNAS." (PMID 36686473, 2022). "We found negative correlations between ZMIZ2 and AR in the cancer tissue samples (r < 0), while the correlation was positive in the normal tissue samples (r > 0)." (PMID 35101047, 2022). "This occurs through reactivation of AR signaling or the emergence of an AR-negative cancer that no longer relies on AR signaling, such as in neuroendocrine CRPC." (PMID 35740556, 2022). "In vitro validation data showed that OCM ABI treatment significantly reduced cancer proliferation in C4-2B cells (p = 0.022), but not in AR- negative PC-3 cells." (PMID 36140255, 2022). "Of note, Xu and his colleague found that AR upregulated GLS1 and increased the glutamine utilization, and therefore, androgen deprivation is considered as an important method to prevent glutamine uptake by cancer cells." (PMID 36077501, 2022).